IL24 (interleukin 24)
Diseases named in the same sentence as IL24 in open-access papers (continued):
Sharing a sentence is not in itself a finding about the gene and the disease.
cancer (continued). "We now expand on this concept and demonstrate the feasibility of producing a tripartite CTV (TCTV) selectively expressing three genes from three distinct promoters that replicate in the cancer cells while producing MDA-7/IL-24 and an imaging gene (i.e., luciferase)." (PMID 33670594, 2021). "Additionally, they found that DOTAP:Chol–mda-7/IL-24 nanoparticles also inhibited growth of murine tumors in syngeneic mouse cancer models." (PMID 35008495, 2021). "Direct anti-cancer effects are evident when MDA-7/IL-24 is overexpressed in cancerous cells." (PMID 35008495, 2021). "Furthermore, neutralizing anti–IL-24 polyclonal antibody inhibited the anti-cancer effects of IL-24 which was earlier induced by Hiltonol treatment." (PMID 33562773, 2021). "Another possible explanation is that IL24 mRNA mediates different cell killing effects between normal and cancer cells depending on reactive oxygen species (ROS), and a number of studies have shown that cancer cells have higher levels of basic ROS than normal cells." (PMID 33014054, 2020). "Interleukin 24 (IL-24) has a radiosensitizing effect in cancer cells." (PMID 32318337, 2020). "Some studies show that IL24 mRNA can inhibit several types of cancer cells, such as prostate cancer, kidney cancer, osteosarcoma, melanoma, colon cancer, cervical cancer, malignant glioma, breast cancer, and lung cancer, without obvious adverse effects on normal cells." (PMID 33014054, 2020). "Thus, ZD55-IL-24 can produce a large amount of exogenous IL-24 in patients and then the produced IL-24 can induce autophagy and cancer-specific apoptosis in patients." (PMID 33257647, 2020). "ZD55-IL-24 can inhibit the growth of tumors and express IL-24 in cancer cells." (PMID 32318337, 2020). "According to that IL-24 is a prospective tumor suppressor cytokine for multiple cancers, it is worth to explore the mechanism by which IL-24 induces apoptosis selectively in cancer cells." (PMID 31956348, 2020). "The study provides a promising strategy for therapy of APL and IL-24 might also be applied as a useful tool in cancer gene therapy as well." (PMID 31145345, 2019). "Additionally, we sought to investigate if MDA-7/IL-24 colocalizes with CHC in cancer cells by using a proximity ligation assay." (PMID 31489119, 2019). "We next raised the question of whether IL-24-mediated DNA damage involves the induction of cancer cell apoptosis." (PMID 31783569, 2019). "Furthermore, attenuation of GLI1-associated DDR by IL-24 increased caspase-3 and PARP activity, resulting in cancer cell apoptosis." (PMID 31783569, 2019). "In contrast, high concentration of IL-24 strongly induces apoptosis of cancer cells." (PMID 31921658, 2019). "Recent evidence suggests IL‐24 is a promising candidate for cancer gene therapy." (PMID 30406970, 2018). "Importantly, we show that overexpression of eIF4A conferred cancer cells with resistance to IL-24-induced cell death and targets the expression of highly structured 5′UTRs mRNAs." (PMID 29786657, 2018). "We also have demonstrated that Sigma 1 Receptor (Sig1R) interacts with IL-24 and that IL-24:Sig1R complex is a critical upstream signal for IL-24-induced ER stress, calcium mobilization, and notably, phosphorylation of eIF2α and apoptosis in cancer cells." (PMID 29786657, 2018). "The results presented here identify PKA as a key mediator of cancer-specific killing by IL-24." (PMID 30424508, 2018). "It was shown that IL‐24 is a selective anti‐cancer agent regulating endoplasmic reticulum stress." (PMID 28781949, 2017). "In another report, it was shown that IL‐24 regulates miR‐221 expression in cancer cells." (PMID 28781949, 2017). "The introduction of immune promoting genes such as GM-CSF can promote the immune responses against tumors, and delivery of TRAIL or IL-24 gene effectively eliminates cancer cells through apoptosis, playing aim portant killing roles not only in CSCs, but also non-CSCs." (PMID 27121064, 2016).
cancer (continued). "In summary, the identification of Sig1R as a key initial mediator of IL-24-cancer-specific apoptosis significantly broadens the therapeutic potential of Sig1R and IL-24 for tumors and provides important knowledge for our understanding of IL-24 as an immune modulating cytokine." (PMID 27271601, 2016). "The transition of IL-24 into a phase II clinical trial reinforces the hypothesis that IL-24 is safe and affords remarkable potential as a cancer gene therapeutic agent." (PMID 27271601, 2016). "One possible reason for this differential killing effect involves inherent biochemical differences between normal and cancer cells (ER stress, ROS production and ceramide), another possibility is that IL-24 is able to target a molecule that only triggers apoptosis in cancer cells." (PMID 27271601, 2016). "In addition, we have shown that Ad.IL-24 and IL-24 protein (generated from Ad.IL-24-infected cells) display a broad cancer-specific pro-apoptotic activity through induction of ER stress, and ceramide production." (PMID 27271601, 2016). "IL24 has synergistic effects in various human cancers when combined with other agents." (PMID 27528029, 2016). "Ad-IL24 was effective in phase I/II clinical trials in patients with advanced cancers." (PMID 27528029, 2016). "Exogenous IL-24 binds with its cognate cell-surface receptors to induce apoptosis in cancer cells." (PMID 27203744, 2016). "Moreover, untransfected neighboring cancer cells can be killed by the bystander effect of mda-7/IL-24." (PMID 27322080, 2016). "IL-24 expression is lost in most cancer cells of human origin." (PMID 27602961, 2016). "Studies using pure MDA-7/IL-24 protein will also be relevant in defining its anti-cancer activity." (PMID 26474456, 2015). "In addition, recombinant MDA-7/IL-24 was shown to be selective against cancer cells from colorectal cancer (CRC) patients." (PMID 25590298, 2015). "Thus, incorporating IL-24 with SDF-1/CXCR4-targeted therapies will be effective in controlling cancer cell metastasis." (PMID 25775124, 2015). "In this study we conducted molecular studies to determine whether IL-24 phosphorylation is important for IL-24-mediated anti-cancer activity." (PMID 26009991, 2015). "Further studies showed that MDA-7/IL-24 could interact with BiP/GRP78 and activate p38 MAPK and GADD expression to selectively cause apoptosis in cancer cells." (PMID 26474456, 2015). "MDA-7/IL-24 functions at multiple levels to promote anti-cancer properties." (PMID 26474456, 2015). "Whether IL-24-mediated inhibition occurs via the AKT/mTOR pathway in human cancers of different origins is unknown and should be investigated." (PMID 26009991, 2015). "All these attributes make MDA-7/IL-24 an ideal candidate for cancer gene therapy." (PMID 24527085, 2014). "Finally, occurrence of bystander effect in humans diagnosed with cancer and treated with Ad-IL24 was demonstrated in a Phase I clinical trial." (PMID 24377906, 2013). "Thus, the existence of a strong correlation between preclinical and clinical study results warrant further testing of IL-24-based cancer therapy either as monotherapy or in combination with other therapeutics in the clinic for treatment of human cancers." (PMID 24377906, 2013). "However, caution needs to be taken when IL-24-based combination therapy are planned and should be tailored based on the cancer type being studied." (PMID 24377906, 2013). "Finally, NSAIDs such as sulindac have been reported to induce sensitization of cancer cells to mda7/IL24-mediated apoptosis." (PMID 23983899, 2013). "Interests in studying whether IL-24 regulates autophagy in cancer cells arises from the initial observation and reports made by our laboratory and others." (PMID 24377906, 2013). "IL24 (0.80 and 0.43, respectively) was found up-regulated in cancer." (PMID 23029164, 2012). "MDA-7/IL-24 displays nearly ubiquitous cancer-specific toxicity." (PMID 22588557, 2012).
cancer (continued). "In order to further detect the role of TrxR1 in IL-24-coupled Bcl-2 S-denitrosylation, we treated these three cancer cells with TrxR1 inhibitor auranofin to detect the alterations of TrxR1 expression, Bcl-2 expression, Bcl-2 S-nitrosylation, and Bcl-2 ubiquitination." (PMID 22629368, 2012). "Viral delivery of mda-7/IL-24 is currently used in clinical trials for various cancers." (PMID 21931671, 2011). "In order to evaluate whether induction of apoptosis in cancer cells by NSAIDs is dependent on mda-7/IL-24 upregulation, we conducted experiments with a lentivirus encoding a siRNA against mda-7/IL-24 that was previously generated by our group." (PMID 21931671, 2011). "Based on our previous observations in other types of cancer we determined whether apoptosis induction by NSAIDs correlates with mda-7/IL-24 induction." (PMID 21931671, 2011). "Moreover, a decreased level of interleukin 24 (IL-24), an apoptotic inducible cytokine, in cancer tissues, attenuates cancer cells from undergoing apoptosis." (PMID 20096135, 2010). "To establish whether the cytokine IL-24 itself has the ability to induce apoptosis of cancer cells, we reasoned that delivery modes other than adenovirus-mediated over-expression of IL-24 should also be able to elicit cell death." (PMID 18074024, 2007). "IL-24 secreted from transfected human embryonic kidney cells (Hek) was shown to elicit apoptosis of various cancer types in vitro while others reported that this form of IL-24 was unable to alter growth characteristics of cancer cells." (PMID 18074024, 2007). "Adding yet another puzzling property to this cytokine it has been reported that infection, transfection or transduction of cells with full length IL-24 leads to secretion of functional cytokine, which then elicits so-called “bystander” effects killing surrounding (receptor-positive) cancer cells." (PMID 18074024, 2007). "Apart from the physiological properties that IL-24 may have under “normal” conditions, far more emphasis has been placed on the tentative ability of this cytokine to selectively induce apoptosis of cancer cells." (PMID 18074024, 2007). "However, there is also evidence that IL-24 mediates bystander effects via receptor-mediated Jak/STAT signaling on receptor-positive surrounding cancer cells that come into contact with the secreted cytokine IL-24." (PMID 18074024, 2007). "Additionally, it provides a comprehensive review of the progress in cancer therapy utilizing IL‐24." (PMID 40338095, 2025). "IL24 was originally discovered to harbor a specific anticancer activity without affecting normal cells, including apoptosis induction, anti-angiogenesis mechanisms, halting invasion, cancer stem cell elimination, radio-sensitization, chemo-sensitization and immune tolerance." (PMID 37270714, 2024). "The cancer cell-specific killing ability of MDA-7/IL-24 cytokine is still an unresolved mystery, which may involve differences in altered metabolism, inherent biochemical and oxidative stress conditions between normal and cancer cells." (PMID 35008495, 2021). "However, IL-24 also displays direct and indirect antitumor activity through induction of autophagy and cancer-specific apoptosis, stimulation of an antitumor immune response, inhibition of angiogenesis, and sensitization of cancer cells to radiation-, chemotherapy- and antibody-induced killing." (PMID 33903973, 2021). "The role of clathrin and mda-7/IL-24 in regulating cell surface receptor degradation can lead to various new downstream pathways, that are different in normal vs. cancer cells, and new potential cancer drug targets maybe identified by exploiting these pathways." (PMID 31489119, 2019). "Similarly, IL-24 exposure also reduced viability of cancer cells on cell growth and apoptosis." (PMID 29786657, 2018). "In addition, IL-24 is an ideal agent for combined cancer therapy." (PMID 27203744, 2016). "However, IL-24 protein expression is lost in a majority of cancer cells of human origin." (PMID 25775124, 2015).
cancer (continued). "Increasing evidence indicates that IL-24 may suppress the growth of cancer stem cells." (PMID 26528857, 2015). "Thus AdLTR2EF1α-IL-24 may become a new therapeutic agent for cancer gene therapy, given the intermediate-length expression and targeted induction of apoptosis." (PMID 26361755, 2015). "Seeing that increased iNOS production and Bcl-2 expression have been associated with several human tumors, this finding on the novel function of MDA-7/IL-24 on regulation of Bcl-2 denitrosylation may provide a valuable mechanism for MDA-7/IL-24 induced cancer-specific apoptosis." (PMID 22629368, 2012). "Conversely, the use of ROS‐generating agents such as arsenic trioxide (As2O3), NSC656240 (dithiophene with applications in cancer), and PK11195 (isoquinoline carboxamide) enhanced the IL‐24‐mediated apoptosis." (PMID 40338095, 2025). "Both IL-24 and WP1066, a specific STAT3 inhibitor, have been investigated as cancer therapies in clinical trials." (PMID 40175348, 2025). "Adenovirus mediated IL‐24 transduction also led to the induction of suppressor of AP‐1(SARI), induced by IFN expression in multiple cancer models." (PMID 40338095, 2025). "IL-24 is a member of the IL-10 cytokine family, signaling via the JAK/STAT3 signaling pathway to induce cancer cell apoptosis." (PMID 40175348, 2025). "Several studies have reported that IL-24 triggers apoptosis in cancer cells, including MDA-MB-231 BC cells, without killing normal cells, making it an ideal target for cancer therapy." (PMID 40175348, 2025). "The induction and activation of mda-7/IL-24 by NSAIDs result in the upregulation of GADD45A and GADD45G, which are crucial for the execution of cancer cell death through JNK activation." (PMID 41018072, 2025). "We have shown that IL-24 induces sustained activation of p38 MAPK activity, contributing to cancer cell apoptosis." (PMID 37444474, 2023). "IL-24 not only activates p38 MAPK but can also activate JNK pathways and inhibit extracellular signal-regulated kinases (ERKs) in cancer cells." (PMID 37444474, 2023). "Differently from IL-24 and IL-12, IL-2 has already been approved by the Food andDrug Administration (FDA) for cancer treatment." (PMID 36206378, 2022). "IL22RA1 was positively correlated with STAT1, STAT3, JAK1, PTPN11, IFNA13, IL24, but negatively correlated with IL10 in specific cancers." (PMID 35874683, 2022). "Initial studies in a Phase I clinical trial in patients with advanced cancers confirmed that intratumoral injection of an adenovirus (Ad) expressing mda-7/IL-24 (Ad.mda-7; INGN 241) is safe and clinically effective in inducing cancer cell-specific apoptosis." (PMID 35008495, 2021). "This virus, also called a cancer terminator virus (CTV), induces cancer-specific replication and a second CMV promoter in the virus promotes MDA-7/IL-24 expression uniquely in cancer cells as a consequence of virus replication." (PMID 35008495, 2021). "The TCTV construct was used to generate Ad.5-TCTV and evaluated for its ability to produce mda-7/IL-24 mRNA and E1A and MDA-7/IL-24 proteins following infection of human cancer cells." (PMID 33670594, 2021). "The CTV induces cancer-selective replication and a second CMV promoter promotes mda-7/IL-24 expression solely in cancer cells as a function of virus replication." (PMID 33670594, 2021). "Thus, modulation of IL-24 to immune cells from cancer patients might be completely different." (PMID 31921658, 2019). "Several studies have shown that the intracellular IL-24 protein binds with BiP/GRP78, inducing ER stress selectively in cancer cells and leads to apoptosis." (PMID 27203744, 2016). "Our results demonstrate that IL-24 phosphorylation is required for inhibiting the AKT/mTOR signaling pathway and exerting its anti-cancer activities." (PMID 26009991, 2015).
cancer (continued). "Based on the extensive preclinical data demonstrating the antitumor activities of IL-24, a Phase I clinical trial was initiated to test the maximum tolerated dose (MTD) and toxicity of Ad-IL24 treatment in cancer patients." (PMID 24377906, 2013). "These preliminary findings concerning IL‐24‐mediated modulation of ER stress along with the UPR/BiP pathway sparked curiosity among researchers, prompting further investigation into IL‐24‐mediated autophagy in cancer cells." (PMID 40338095, 2025). "IL-24 can induce apoptosis in cancer cells, including MDA-MB-231 cells, without affecting normal cells, an attractive feature for a potential therapeutic target." (PMID 40175348, 2025). "Research indicates that while IL‐24 mRNA is detectable, protein expression is absent in both patient tissues and human cancer cell lines." (PMID 40338095, 2025). "Both IL-24 and WP1066 have been studied as cancer therapies in clinical trials." (PMID 40175348, 2025). "It is important to note that this review on IL‐24‐mediated cancer cell apoptosis is not comprehensive." (PMID 40338095, 2025). "In contrast to the three cancers tested, nonmalignant cells had the lowest basal levels of IL24 RNA, and they were the least sensitive to WX8." (PMID 38414326, 2024). "While IL-24 has a specific, lethal effect on cancer cells, it does not adversely affect normal cells or tissues." (PMID 38711526, 2024). "Albeit signaling pathways triggered by IL-24 have been the focus of intensive studies, the mechanisms governing cancer-specific apoptosis triggered by IL-24 are nevertheless not well understood." (PMID 37280571, 2023). "MDA-7/IL-24 cytokine has shown potent antitumor properties in various types of cancer without exerting any significant toxicity on healthy cells." (PMID 35752792, 2022). "An intracellular function of IL-24 has previously been suggested, since a nonsecretable version of IL-24 (also known as Mda-7) was found to be as efficient to induce apoptosis in a carcinoma cell line as wild-type IL-24." (PMID 35819408, 2022). "Conditional replication of the TCTV is regulated by a cancer-selective (truncated PEG-3) promoter, the therapeutic component, MDA-7/IL-24, is under a ubiquitous (CMV) promoter, and finally the imaging capabilities are synchronized through another cancer selective (truncated tCCN1) promoter." (PMID 33670594, 2021). "We found that MDA-7/IL-24 (either by Ad-mediated delivery or with pure recombinant protein) downregulated DICER in a reactive oxygen species-dependent manner and the overexpression of DICER partially rescued MDA-7/IL-24-mediated cell death in cancer cells." (PMID 35008495, 2021). "IL‐24 has been shown to promote the populations of CD4+ and CD8+ T cells in diverse cancer models." (PMID 33274495, 2021). "In both cancer contexts, addition of MDA-7/IL-24 helps overcome resistance to temozolomide." (PMID 35008495, 2021). "Previous studies demonstrated that IL-20 subfamily cytokines induce apoptosis of different cancer and non-cancerous epithelial cells, therefore we investigated the effect of IL-24 on cell viability." (PMID 34078403, 2021). "In all subgroups, the IL24 mRNA upregulation had the ability to distinguish cancer from noncancer tissue with area under the curves (AUCs) of the summary receiver operating characteristic (sROC) higher than 0.85." (PMID 33014054, 2020). "According to the results of sROC, IL24 mRNA also had the ability to distinguish between cancer and noncancer tissues in HNSCC and its subtypes, respectively." (PMID 33014054, 2020). "The expression of the IL24 mRNA in HNSCC and its subgroups and the ability of the IL24 mRNA to distinguish cancer tissue from noncancer tissue are rarely studied." (PMID 33014054, 2020). "Of note, IL24 was also induced by knocking-down STING and STING activation, which might be the core mediator to induce apoptosis in cancer cells." (PMID 31903134, 2020).